SLC6A4 (solute carrier family 6 member 4)
Diseases named in the same sentence as SLC6A4 in open-access papers (continued):
Sharing a sentence is not in itself a finding about the gene and the disease.
nicotine dependence (8 papers, 2011 to 2022). Physical and psychological dependence on nicotine. "The present study aimed to analyse the association of two regulatory VNTRs in the SLC6A4 gene and their interaction in the nicotine dependence of Vietnamese men." (PMID 30559666, 2018). "We have analyzed the involvement of SLC6A4 genetic variations in nicotine dependence and identified significant associations of the STin2 variant with specific measures of nicotine dependence." (PMID 30559666, 2018). "Our study was designed to analyse the potential genetic association of the two regulatory VNTRs within the SLC6A4 gene in nicotine dependence." (PMID 30559666, 2018). "One recent study found an association between the polymorphic variable number tandem repeat (VNTR) in the SLC6A4 gene and increased risk for tobacco use disorder." (PMID 28724413, 2017). "The aim of this study was to determine if variable number of tandem repeats (VNTR) in the second intron (STin2) of the serotonin transporter (SLC6A4) gene was associated with tobacco use disorder, successful smoking cessation, or smoking characteristics." (PMID 24968820, 2014). "While there are now many reports on the association between 5-HTTLPR polymorphism of the SLC6A4 gene and smoking behavior, there are only few studies on the SLC6A4 gene STin2 polymorphism in tobacco use disorder." (PMID 24968820, 2014). "Our study aimed to find association between nicotine dependence and SLC6A4." (PMID 30559666, 2018). "Association between the SLC6A4 polymorphisms and nicotine dependence is controversial." (PMID 30559666, 2018). "The SLC6A4 gene is the most frequently studied polymorphism in depression and tobacco use disorder." (PMID 24968820, 2014). "An altered function of the STin 2 VNTR in the SLC6A4 gene may be involved in tobacco use disorder since the STin2.12 allele has been reported to be a transcriptional enhancer associated with susceptibility to substance abuse." (PMID 24968820, 2014). "Other studies focused on the involvement of the SLC6A4/5-HTTLPR (serotonin transporter) gene in the pathophysiology of nicotine dependence." (PMID 35455685, 2022). "For example, the genetic interaction between HTTLPR and STin2 VNTRs within the SLC6A4 gene in regulation of nicotine dependence was evaluated." (PMID 33784353, 2021). "Results from present study support the findings from existing literature and give further evidence for the involvement of SLC6A4 in nicotine dependence." (PMID 30559666, 2018). "Present study advances our knowledge about the nicotine addiction by describing the interaction between two functional VNTR loci in SLC6A4 gene in modifying the smoking behavior." (PMID 30559666, 2018). "The Fagerström Test (FTND) was used to evaluate the nicotine dependence and PCR was used to determine the SLC6A4 HTTLPR and STin2 VNTRs." (PMID 30559666, 2018). "Stratification analysis was used to find the genetic interaction between these two VNTRs in nicotine dependence as they may synergistically regulate the SLC6A4 expression." (PMID 30559666, 2018). "This may indicate that the STin 2 VNTR polymorphism in the SLC6A4 gene could influence an individual’s vulnerability to develop tobacco use disorder rather than a substance use disorder." (PMID 24968820, 2014). "Our present study significantly advances existing literature on the role of the SLC6A4 in nicotine dependence as it indicates differential and interactive effect of HTTLPR and STIn2 in nicotine dependence." (PMID 30559666, 2018).
psychosis (8 papers, 2010 to 2025). "None of the glutamatergic and serotonergic genetic variants were found to moderate the effect of psychosis on obsession and compulsion (SLC6A4, SLC1A1 and HTR2C) survived the multiple comparisons correction." (PMID 38652060, 2024). "Nevertheless, our identification of several genetic variants in the serotonin pathway (SLC6A4, HTR2C) moderating the psychosis–obsession–compulsion pathway is notable, and may offer clues to future preventive or therapeutic approaches." (PMID 38652060, 2024).
Tinnitus (8 papers, 2016 to 2021). Tinnitus is an auditory perception that can be described as the experience of sound, in the ear or in the head, in the absence of external acoustic stimulation. "The 5-HTTLPR polymorphism in the promoter of the serotonin transporter gene SLC6A4 was found associated with greater tinnitus severity." (PMID 33255712, 2020). "This study linked a polymorphism in the SLC6A4 promoter with neurophysiological symptoms in tinnitus patients." (PMID 28533738, 2017). "The gene SLC6A4 regulates serotonin neurotransmission and has been evaluated for tinnitus-association." (PMID 28533738, 2017). "In addition, the importance of serotonergic neural transmission was reported in a genetic study, which demonstrated that the polymorphism of the serotonin transporter gene (SLC6A4) was associated with the visual analog scale of tinnitus." (PMID 33513909, 2021). "However, the genotype variant of the SLC6A4 polymorphic promoter region seems associated with the limbic and autonomic nervous system symptoms of patients with tinnitus." (PMID 32747715, 2020). "As a consequence of these findings, one could envisage that SLC6A4 variants could become markers of tinnitus distress, and that serotonin reuptake inhibitors could be targeted at subtypes of patients with tinnitus and depression in the presence of the risk allele." (PMID 27594824, 2016).
breast carcinoma (7 papers, 2015 to 2025). "In contrast, SLC5A11, SLC6A4 and MRPS12 were the most downregulated in HIV-positive breast cancer with a long2foldchange of −6.7, 6.5 and −4.7, respectively." (PMID 33194615, 2020). "To biologically validate these findings, we performed IHC assay to detect the expression of four proteins (PROM1, LAMB3, SLC6A4, and MRPS12) generated from those genes found to be differentially expressed in HIV-positive breast cancer samples." (PMID 33194615, 2020).
COVID-19 (7 papers, 2021 to 2025). A disease caused by infection with severe acute respiratory syndrome coronavirus 2. "Greater COVID-19-related prenatal stress was significantly associated with higher infants’ SLC6A4 methylation in seven CpG sites." (PMID 34341434, 2021). "For infants, SLC6A4 methylation was positively and significantly associated with COVID-19-related prenatal stress at seven CpG sites (i.e., 1, 2, 6, 8, 9, 10, and 12)." (PMID 34341434, 2021). "Network pharmacology analyses identified 6 potential targets (IL6, DPP4, MIF, PRF1, SERPING1, and SLC6A4) for emetine in anti-LUAD/COVID-19." (PMID 35733175, 2022). "In addition, we evaluated the potential bindings of emetine with the LUAD/COVID-19 targets (SLC6A4, MIF, DPP4, PRF1, SERPING1, and IL6)." (PMID 35733175, 2022). "In more specific terms, pregnant women experiencing greater COVID-19-related prenatal stress may give birth to infants who present higher levels of SLC6A4 methylation and temperament dysregulation at 3 months." (PMID 34341434, 2021). "The current study is among the first to show a greater impact of exposure to the COVID-19 pandemic on levels of maternal and infant methylation of target stress-related genes (i.e., NR3C1 and SLC6A4) in late gestation, as compared to earlier exposures." (PMID 36114180, 2022). "Notably, in the present study, a significant effect of COVID-19-related prenatal stress emerged for infants’ SLC6A4 methylation, but not for mothers." (PMID 34341434, 2021).
emotional dysregulation (7 papers, 2012 to 2025). "However, in the absence of the psychological health data in our cohort, we cannot determine whether the observed association of the SLC6A4 gene with shorter survival times is due to its role in psychological distress or due to other biological roles of the SLC6A4." (PMID 22911682, 2012).
lung carcinoma (7 papers, 2020 to 2025). "5‐Hydroxytryptamine may enhance tumorigenicity and increase the risk of distant metastasis in non‐small cell lung cancer patients through 5‐HT‐c‐Myc‐SLC6A4 axis, suggesting that SLC6A4 was an important molecule in tumorigenesis and metastasis." (PMID 38352696, 2024). "In addition, SLC6A4 variants are a risk factor for coprous obstructive pulmonary disease with lung cancer." (PMID 36507532, 2022).
attention deficit-hyperactivity disorder (6 papers, 2012 to 2025). A disorder characterized by a marked pattern of inattention and/or hyperactivity-impulsivity that is inconsistent with developmental level and clearly interferes with functioning in at least two settings (e.g. at home and at school). "Haplotypes incorporating STin2 and the SLC6A4 5-HTTLPR polymorphism have been associated with sleep apnoea, postpartum depression and attention deficit hyperactivity disorder." (PMID 22384070, 2012).
behavioral disorders (6 papers, 2008 to 2022). "However, inconsistent with previous research which has found the rs3813034 of SLC6A4 is a putative risk factor for PD and other behavioral disorders that involve dysregulation of serotonergic neurotransmission." (PMID 32723321, 2020). "Persistent changes in SLC6A4 gene expression patterns, have been shown to correlate with mood and aggressive behavior disorders." (PMID 36212196, 2022). "Also implicated in moderating the link between prenatal maternal stress and aggressive behavior disorders is the serotonin transporter (SERT) gene polymorphic region (5-HTTLPR) coded by the SLC6A4 gene." (PMID 36212196, 2022).
colorectal cancer (6 papers, 2012 to 2025). A primary or metastatic malignant neoplasm that affects the colon or rectum. "It has been reported that variants in the SLC6A4 gene were associated with unfavorable prognosis in patients with colorectal cancer." (PMID 38352696, 2024). "At the same time, the SLC6A4 variant was associated with low survival in colorectal cancer patients." (PMID 36507532, 2022). "Interestingly IL-6 was previously reported to be associated with variations in the SLC6A4 gene (see the previous paragraph), which also seems to be a mediator of tumor progression in colorectal cancer." (PMID 22911682, 2012). "While our results remain to be replicated in other patient cohorts, we suggest that the genetic variations in the SLC6A4 gene contribute to poor survival in colorectal cancer patients." (PMID 22911682, 2012). "In this study, we hypothesized that genetic variants located within the SLC6A4, BDNF, and AVPR1B genes are associated with prognosis in colorectal cancer patients." (PMID 22911682, 2012). "Although our approach did not include all variations in the SLC6A4 gene, these results suggest the association of multiple SLC6A4 variations with prognosis in colorectal cancer patients." (PMID 22911682, 2012). "Consequently, in the present study, we have aimed to test the associations of five genetic variations in stress response genes (SLC6A4, BDNF, and AVPR1B) with clinical outcomes in a population-based cohort of 280 colorectal cancer patients from Newfoundland and Labrador (NL)." (PMID 22911682, 2012).
sexual dysfunction (6 papers, 2016 to 2024). Disturbances in sexual desire and the psychophysiologic changes that characterize the sexual response cycle and cause marked distress and interpersonal difficulty. "In our analyses, SLC6A4 appears highly significantly associated (i.e. q-value << 0.05) with a range of different sexual dysfunctions (e.g. ejaculation failure and female sexual dysfunction)." (PMID 34679164, 2021). "The sodium-dependent serotonin transporter (SLC6A4; Uniprot ID P31645) is inhibited by the serotonin norepinephrine reuptake inhibitor Venlafaxine, which in turn has been associated with sexual-dysfunction." (PMID 34679164, 2021). "A previous study reported the influence of SLC6A4 in sexual dysfunction and weight gain among risperidone treated patients." (PMID 28018217, 2016).
fibromyalgia (5 papers, 2006 to 2024). A chronic disorder of unknown etiology characterized by pain, stiffness, and tenderness in the muscles of neck, shoulders, back, hips, arms, and legs. "Based on the SLC6A4 gene’s putative involvement in chronic pain states such as fibromyalgia and the fact that such conditions may be accompanied by experimental deficits in pain regulation we hypothesized that the gene would also be associated with CPM-response in healthy individuals." (PMID 21464942, 2011).
glioma (5 papers, 2023 to 2025). A benign or malignant brain and spinal cord tumor that arises from glial cells (astrocytes, oligodendrocytes, ependymal cells). "Its uptake into glioma cells has been shown to occur through a SLC6A4/SERT-dependent mechanism." (PMID 37298344, 2023).
Hypertension (5 papers, 2013 to 2025). The presence of chronic increased pressure in the systemic arterial system. "In vivo, MAOA was induced during aging and hypertension but the expression of the corresponding serotonin uptake receptor (SLC6A4) was reduced and enzymes that reduce either oxidative stress (CAT) or accumulation of 5-hydroxyindolacetaldehyde (ALDH2) were induced." (PMID 37371593, 2023).
neuroblastoma (5 papers, 2016 to 2025). Neuroblastoma (NB) is the most common solid, extracranial childhood tumor. "For example, quetiapine, as an atypical antipsychotic drug, is capable of reducing DNAm level of the promoter region of SLC6A4 (serotonin transporter gene) in human neuroblastoma cells." (PMID 40710357, 2025). "mRNA expression of SLC6A4 in the neuroblastoma cell lines was examined by qPCR (threshold cycle, Ct range = 30–32) and the protein expression was confirmed by Western blot." (PMID 27716787, 2016).
alcohol use disorder (4 papers, 2016 to 2025). "Among the initial candidate genes explored for their potential association with the risk of alcohol use disorder, SLC6A4 was prioritized." (PMID 38491208, 2024). "Therefore, assessing the gene expressions of P2X4, P2X7, and SLC6A4 is a suitable way to diagnose hangover-related emotional anxiety and alcohol use disorder." (PMID 38491208, 2024). "The present study explored the relationship between SLC6A4, TPH2, and GALM genes and neurocognitive impairment in HIV-infected alcohol abusers." (PMID 27069689, 2016).
coronary artery disease (4 papers, 2017 to 2025). "Our research aimed to determine whether the bi-allelic 5-HTTLPR, tri-allelic 5-HTTLPR (rs25531), and STin2 polymorphisms of SLC6A4 were associated with an increased risk of coronary artery disease (CAD) in the North Indian population of Jammu region in Jammu and Kashmir state of India." (PMID 40369544, 2025).
Dystonia (4 papers, 2017 to 2022). An abnormally increased muscular tone that causes fixed abnormal postures. "This study investigates the percentage of DNA methylation of the gene encoding for the serotonin reuptake transporter (SLC6A4) in dystonia patients and the associations between methylation levels and presence and severity of psychiatric symptoms." (PMID 36503539, 2022). "This is the first time that the relationship between methylation of the SLC6A4 gene and depressive symptoms was investigated in a dystonia cohort." (PMID 36503539, 2022). "The aim of this study is to investigate the percentage of DNA methylation of the promoter region of the SLC6A4 gene in blood from large cohort of dystonia patients and compare this to healthy controls." (PMID 36503539, 2022). "The gene encoding for 5-HTT (SLC6A4) is a promising candidate gene for studying the pathophysiology and involvement of serotonergic metabolism in psychiatric symptoms observed in dystonia." (PMID 36503539, 2022). "Concluding, this study showed for the first time the role of SLC6A4 and non-motor symptoms in a relatively large cohort of dystonia patients." (PMID 36503539, 2022).
functional dyspepsia (4 papers, 2014 to 2023). "The serotonin transporter (SLC6A4) is associated with functional dyspepsia in H. pylori infection." (PMID 37275170, 2023). "Because of their potential role in functional dyspepsia current study aimed to determine the DNA methylation status of SLC6A4 gene in the gastric mucosa in FD." (PMID 25148529, 2014). "We investigated DNA methylation status of SLC6A4 gene in the gastric mucosa from functional dyspepsia (FD) because of their potential role in dyspeptic symptoms." (PMID 25148529, 2014). "Fourteen genes corresponding to two gene sets were identified, and the functional dyspepsia-related genes targeted by the activated F. fructus compound were ADRA2A, BDNF, CCK, CRP, GCG, JUN, Kcnh2, PTGS1, PTGS2, Pyy, SLC6A4, and TRPV." (PMID 37375548, 2023).
Hyperglycemia (4 papers, 2012 to 2023). An increased concentration of glucose in the blood. "In particular, we investigated the relationship between GDM, the most common cause of maternal hyperglycemia in pregnancy, and placental DNA methylation of the SLC6A4 gene." (PMID 28650965, 2017). "This suggests that intrauterine hyperglycemia affects SLC6A4 promoter hypermethylation and offspring development." (PMID 36431006, 2022).
stress-related disorder (4 papers, 2023 to 2025). Stress-related disorders are mental health disorders that are a result of an atypical response to both short and long-term anxiety due to physical, mental, or emotional stress. "Building on these findings, our research focused on the dynamics of DNA methylation of the candidate genes, BDNF, COMT, and SLC6A4, involved in the pathophysiology of stress-related disorders, i.e., pathways involved in neurotransmitter systems and neuroplasticity." (PMID 37754245, 2023).
gestational diabetes mellitus (3 papers, 2017 to 2024). "We tested the hypothesis that gestational diabetes mellitus (GDM) alters the DNA methylation pattern of the fetal serotonin transporter gene (SLC6A4), and examined the functional relevance of DNA methylation for regulation of the SLC6A4 expression in the human placenta." (PMID 28650965, 2017).
lung adenocarcinoma (3 papers, 2019 to 2025). A carcinoma that arises from the lung and is characterized by the presence of malignant glandular epithelial cells. "However, BMP2, SELP, and SLC6A4 were significantly down-regulated in lung adenocarcinoma cells compared with NHBE cells." (PMID 36147496, 2022).
melanoma (3 papers, 2022 to 2025). A malignant, usually aggressive tumor composed of atypical, neoplastic melanocytes. "Slc6a4, also known as 5‐HTT or SERT, is an integral membrane protein that terminates and recycles serotonin in presynaptic vesicles in a sodium‐dependent manner and stores 5‐HT in some cells, such as platelets, human melanoma and keratinocyte cell lines." (PMID 39910963, 2025).
Tremor (3 papers, 2015 to 2025). An unintentional, oscillating to-and-fro muscle movement about a joint axis. "Motor symptoms of tremor and rigidity were analyzed to understand their association with SLC6A4 polymorphisms." (PMID 31024427, 2019).
alexithymia (2 papers, 2023 to 2024). An agnosia that is a deficiency in understanding, processing, or describing emotions. "The main candidate genes associated with alexithymia are from the serotoninergic pathway (SLC6A4, HTR1A and HTR2A) and neurotransmitter metabolism (DRD2/ANKK1, COMT, BDNF, and OXTR)." (PMID 39202385, 2024). "Concerning alexithymia, there have been studies searching for the role of SLC6A4 gene variants." (PMID 39202385, 2024). "Interestingly, SLC6A4 association with alexithymia emerged in two studies." (PMID 36729042, 2023).
heart failure (2 papers, 2019 to 2021). Inability of the heart to pump blood at an adequate rate to meet tissue metabolic requirements. "A repeat length polymorphism in the promoter region of the serotonin transporter solute carrier family 6 member 4 (SLC6A4, also known as 5-HTT and SERT)) gene has been related to mPAP in heart failure." (PMID 31771195, 2019).